SRSF3 (serine and arginine rich splicing factor 3)
Diseases named in the same sentence as SRSF3 in open-access papers (continued):
Sharing a sentence is not in itself a finding about the gene and the disease.
osteosarcoma (8 papers, 2016 to 2024). A usually aggressive malignant bone-forming mesenchymal neoplasm, predominantly affecting adolescents and young adults. "Higher levels of ZFAS1 or SRSF3 were linked to a poor prognosis of osteosarcoma." (PMID 35184675, 2022). "Furthermore, higher levels of SRSF3 were associated with significantly shorter overall survival in osteosarcoma patients." (PMID 35184675, 2022). "Specifically, studies have shown that SRSF1 influences the migration, invasion, proliferation, and apoptosis of osteosarcoma cells, while SRSF3 regulates ILF3 RNA splicing to control osteosarcoma growth." (PMID 39286028, 2024). "We also re-analyzed a previous dataset (GSE22149), which applied a SpliceArray to analyze genome-wide splicing targets of SRSF3 in human osteosarcoma U2OS cells." (PMID 36835286, 2023). "Under arsenite-induced oxidative stress, SRSF3 is neddylated in Lys85 and promotes stress granule aggregation in human osteosarcoma U2OS cells." (PMID 37416784, 2023). "SRSF3 regulated the expressions or splicing events of nearly 200 genes in osteosarcoma cells based on global profiling data." (PMID 35184675, 2022). "Our findings show that ZFAS1 plays an essential role in osteosarcoma progression by stabilizing the SRSF3 protein." (PMID 35184675, 2022). "First, we examined the expressions of ZFAS1 and SRSF3 in osteosarcoma patients and their relationship to prognosis outcomes." (PMID 35184675, 2022). "The role of ZFAS1 regulated osteosarcoma cells proliferation and metastasis through SRSF3 was subsequently explored." (PMID 35184675, 2022). "ZFAS1 was found to be upregulated in osteosarcoma and be positively correlated with SRSF3 protein levels." (PMID 35184675, 2022). "This study discovered that ZFAS1 was upregulated in osteosarcoma patient tissues, which correlates with elevated SRSF3 protein levels." (PMID 35184675, 2022). "In particular, SRSF3 was shown to regulate the alternative splicing of genes related to cell proliferation and cell cycle progression in osteosarcoma." (PMID 32023846, 2020). "We investigated the effect of SRSF3 silencing on clonogenicity and metastatic potential of osteosarcoma U2OS cells." (PMID 28039456, 2017). "We also found that reduced expression of SRSF3 inhibited clonogenicity and suppressed metastatic abilities including invasion and migration, indicating that SRSF3 is responsible for the malignant phenotypes of osteosarcoma U2OS cells." (PMID 28039456, 2017). "Functional studies demonstrated that ZFAS1 depletion could inhibit osteosarcoma cells proliferation and metastasis through SRSF3." (PMID 35184675, 2022). "An increased level of SRSF3 was detected in osteosarcoma tissue." (PMID 35184675, 2022). "Based on the findings of this study, ZFAS1 stabilized SRSF3 protein in osteosarcoma cells." (PMID 35184675, 2022). "Furthermore, exogenous SRSF3 expression in ZFAS1-depleted osteosarcoma cells restored SRSF3 expression while simultaneously inhibiting cell proliferation and metastasis." (PMID 35184675, 2022). "We discovered that SRSF3 was increased in osteosarcoma tissues, consistent with previous research." (PMID 35184675, 2022). "This interaction promotes osteosarcoma progression by preventing SRSF3 degradation." (PMID 35184675, 2022). "Further functional experiments revealed that ZFAS1 could stabilize SRSF3 protein, increasing its level in osteosarcoma cells." (PMID 35184675, 2022). "Compilation of these findings suggests that ZFAS1 promotes osteosarcoma progression through SRSF3." (PMID 35184675, 2022). "We hypothesized in our study that the lncRNA ZFAS1 promotes osteosarcoma by directly binding to and stabilizing SRSF3." (PMID 35184675, 2022). "Interestingly, we discovered that a major splicing factor, serine, and arginine-rich splicing factor 3 (SRSF3), was also upregulated in osteosarcoma using TCGA datasets." (PMID 35184675, 2022). "We investigated here the oncogenic functions of SRSF3 in osteosarcoma U2OS cells." (PMID 28039456, 2017).
osteosarcoma (continued). "In this study, we investigated the oncogenic function of SRSF3 in osteosarcoma U2OS cells." (PMID 28039456, 2017). "Thus, we hypothesized that ZFAS1 has the potential to regulate osteosarcoma progression through directly binding to and stabilizing SRSF3." (PMID 35184675, 2022). "The exact mechanism by which SRSF3 is increased in osteosarcoma remains unknown." (PMID 35184675, 2022). "The biologic function of ZFAS1 in osteosarcoma cells was explored based on the upregulation of both ZFAS1 and SRSF3 in osteosarcoma." (PMID 35184675, 2022). "SRSF3 has been recently reported to regulate alternative splicing and gene expression of forkhead box M1 (FoxM1), polo-like kinase 1 (PLK1), and cell division cycle 25B (Cdc25B) in U2OS osteosarcoma cells." (PMID 28039456, 2017).
ovarian carcinoma (8 papers, 2012 to 2026). A malignant neoplasm originating from the surface ovarian epithelium. "Knockdown of SRSF3 expression causes growth inhibition or apoptosis of ovarian cancer cells, depending on the extent of SRSF3 knockdown." (PMID 26282282, 2015). "In order to determine the mechanisms underlying the role of SRSF3 in ovarian cancer, we conducted human exon microarray analysis to examine the genome-wide profiles of gene expression and splicing in A2780/SRSF3si2 cells with or without SRSF3 knockdown." (PMID 26282282, 2015). "As such, aberrant expression of RNA splice factors such as SRSF3 is associated with ovarian cancer, and we find that Drp1(-/17) is more strongly expressed in tumors with documented CDK12 mutations, a cyclin-dependent kinase that has been associated with regulation of the spliceosome." (PMID 39191946, 2024). "The mechanism underlying the role of SRSF3 in ovarian cancer remains to be addressed." (PMID 26282282, 2015). "In ovary cancer cells, SRSF3 inhibits DNA double-strand break, and promotes homologous recombination-mediated DNA repair." (PMID 37416784, 2023). "This new function of SRSF3 not only explains why overexpression of SRSF3 is required for ovarian cancer cell growth and survival but also offers a new insight into the mechanism of the neoplastic transformation." (PMID 26282282, 2015). "This novel function explains why overexpression of SRSF3 is required for ovarian cancer cell growth and survival but also offers a new insight into the mechanism of the neoplastic transformation." (PMID 26282282, 2015). "Additionally, SRSF3 overexpression is essential for ovarian cancer cell growth and survival, while its knockdown impairs DNA repair activity, with underlying mechanisms explored in prior research." (PMID 41099605, 2026). "Additionally, SRSF3 is upregulated in human ovarian cancer and its knockdown leads to apoptosis of cancer cell, which indicates SRSF3 expression may significantly correlate to survival and immune cell infiltration." (PMID 35494088, 2022). "Our previous work found that serine/arginine-rich splicing factor 3 (SRSF3) was overexpressed in human ovarian cancer and the overexpression of SRSF3 was required for ovarian cancer cell growth and survival." (PMID 26282282, 2015). "Subsequently, a series of studies have revealed that SRSF3 knockdown induces significant high level of caspase-3 cleavage, condensed and fragmented nuclei, and cell proliferation inhibition in U2OS, SW480 (a human colon adenocarcinoma cell line) 125, and ovarian cancer cells." (PMID 37416784, 2023).
gastric cancer (7 papers, 2022 to 2024). A primary or metastatic malignant neoplasm involving the stomach. "In gastric cancer cells, the inhibition of SRSF3 alleviated proliferation and migration by regulating the PI3K/AKT/mTOR signaling pathway." (PMID 36901944, 2023). "In colon, esophagus, lung, and stomach cancer tissues, the SRSF3 mRNA level was upregulated compared to that in the normal tissues." (PMID 36344491, 2022).
fatty liver disease (6 papers, 2020 to 2026). A reversible condition wherein large vacuoles of triglyceride fat accumulate in liver cells via the process of steatosis. "SRSF3 protein is proteosomally degraded in metabolic-dysfunction associated fatty liver disease (MAFLD) and metabolic-dysfunction-associated steatohepatitis (MASH)." (PMID 41480745, 2026). "The NEDDylation of SRSF3 occurs at Lys11, and the mutation of SRSF3 (SRSF3-K11R) prevents its degradation and alteration in RNA splicing, which alleviates hepatic steatosis, fibrosis, and inflammation." (PMID 39697538, 2024). "Taken together, our data primarily demonstrate that loss of SRSF3 weakens the clearance of fatty acids by impairing lipophagy in the progression of nonalcoholic fatty liver disease, indicating a novel potential therapeutic target for fatty liver disease treatment." (PMID 36764525, 2023). "On this basis, the result above implies that intervening with the neddylation of SRSF3 contributes to its stability and accumulation, which is beneficial for preventing hepatic steatosis, fibrosis, and inflammation." (PMID 33195347, 2020). "We found that SRSF3 were significantly reduced in biopsies of human fatty liver disease." (PMID 36764525, 2023). "Although SRSF3 protein levels were decreased in fatty liver disease, the levels of its mRNA and the ratio of SRSF3 mRNA isoforms did not change." (PMID 33716968, 2021). "However, unlike SRSF3, neddylation of SREBP1c competing with its ubiquitination facilitates its stability and, rather than promoting its degradation via proteasome, eventually contributes to hepatic steatosis." (PMID 33195347, 2020).
liver cancer (5 papers, 2022 to 2025). An epithelial or non-epithelial malignant neoplasm that arises from the liver. "The results indicate that IGF2 overexpression in conjunction with reduced SRSF3 splicing activity could be a major cause of DNA damage and driver of liver cancer." (PMID 35615981, 2022). "IGF2 overexpression and SRSF3 loss could thus be a major cause of DNA damage and liver cancer." (PMID 35615981, 2022). "Consistent with the previous report, our result also showed higher DEN-induced liver cancer incidence in Srsf3 WT male mice than in Srsf3 WT female mice." (PMID 40568073, 2025). "In DEN-induced liver cancer, a total of 677 Srsf3-regulated splicing events of 575 genes were detected by rMATS." (PMID 40568073, 2025). "We found that both male and female mice with Srsf3 KO show a much higher incidence in DEN-induced liver cancer formation (p < 0.0001) when compared to WT Srsf3 mice." (PMID 40568073, 2025). "Subsequently, we identified the top 25 each of upregulated and down-regulated genes in Srsf3 KO liver cancer tissues and verified the expression of top 15 upregulated and downregulated genes by NanoString analysis (in red)." (PMID 40568073, 2025). "Moving forward in high reverence is to investigate how Srsf3 regulates the expression of ERα as a target for understanding liver carcinogenesis and for development of potential new liver cancer therapies." (PMID 40568073, 2025). "Srsf3 KO in hepatocytes enhances DEN-induced liver cancer and disrupts the sex disparity in DEN-induced liver cancer." (PMID 40568073, 2025). "We further verified the increased expression of Sox4, E2f1, Trpv4, and Trim6 in DEN-induced, Srsf3 KO liver cancer tissues by qRT-PCR." (PMID 40568073, 2025). "Western blot analysis and immunostaining of DEN-induced liver cancer tissues showed the decreased level of ERα protein in the Srsf3 KO female and male livers." (PMID 40568073, 2025). "Deletion of insulin‐like growth factor 2 (IGF2) prevents liver cancer in the serine‐arginine rich splicing factor 3 (SRSF3) knockout mouse model by restoring DNA repair enzymes and preventing DNA damage." (PMID 35615981, 2022). "We discovered that Srsf3 plays opposite roles in the development of breast and liver cancers." (PMID 40568073, 2025). "Surprisingly, we found Srsf3 also contributes the gender disparity in liver cancer." (PMID 40568073, 2025). "However, the molecular mechanisms of how Srsf3 function at physiological level and in the development of liver cancer remains to be determined." (PMID 40568073, 2025). "Interestingly at 6th month of animal age, 11 out of the 43 validated genes exhibited the same up- or down-regulation in DEN-induced Srsf3 KO liver cancer when compared to DEN-induced Srsf3 WT liver cancer at the 18 months of observation." (PMID 40568073, 2025). "Srsf3 KO in our study decreased the expression of ERα and Foxa1–3 and its downstream genes Lifr and Egfr but increased Myc expression both in female and male livers, thereby promoting liver cancer formation by disrupting sex disparity." (PMID 40568073, 2025). "Moreover, Srsf3 KO suppresses the expression of ERα and Foxa genes to reduce Lifr and Egfr but induce Myc expression and promote liver cancer in female mice." (PMID 40568073, 2025). "Surprisingly, Srsf3 knockout decreases the gender disparity in the development of liver cancer." (PMID 40568073, 2025). "However, Srsf3 was found to be tumor suppressive in DEN-induced liver cancer." (PMID 40568073, 2025). "We found that Srsf3 KO in liver could promote the development of DEN-induced liver cancer." (PMID 40568073, 2025). "Our RNA-seq and RT-qPCR analyses of DEN-induced Srsf3 WT and Srsf3 KO liver cancer show significant reduction of Lifr and Egfr expression, but increased expression of oncogenic Myc in DEN-induced Srsf3 KO liver cancer in both male and female mice." (PMID 40568073, 2025).
liver cancer (continued). "For example, the splicing factor SRSF3 can directly bind to LNCAROD, inducing PKM isoform switching to PKM2 and enhancing aerobic glycolysis in liver cancer cells, promoting tumor malignancy and chemotherapy resistance." (PMID 38785569, 2024). "In the DEN-induced mouse liver cancer model, we observed that ~24% of the mice with liver-specific KO of Srsf3 died by one month-old, whereas no early death was observed in the mice bearing WT Srsf3 or hetSrsf3 KO." (PMID 40568073, 2025). "RNA-seq analyses showed that DEN-induced Srsf3 KO liver cancer in both female and male mice exhibited a significantly reduced expression of Foxa1/2/3 and ERα than DEN-induced Srsf3 WT liver cancer, which could be verified by quantitative RT-PCR." (PMID 40568073, 2025).
lung carcinoma (5 papers, 2018 to 2024). "SRSF3 is overexpressed in many cancers including lung cancer, probably due to gene amplification." (PMID 34065983, 2021). "It is thus likely that SRSF3 also acts as a proto-oncogene in lung cancer." (PMID 34065983, 2021). "Overexpression of several SR and SR-like proteins, in particular SRSF1, SRSF3, SRSF6 and TRA2β, was observed in lung cancer." (PMID 34065983, 2021).
head and neck cancer (4 papers, 2019 to 2025). A primary or metastatic malignant neoplasm affecting the head and neck. "The specific influence of individual splicing factors on the efficacy of chemotherapy drugs used in head and neck cancer has only been studied in the case of SRSF3, which was shown to be associated with reduced sensitivity of cancer cells to Paclitaxel (PTX) treatment." (PMID 39000035, 2024). "In head and neck cancer, reduction of core splicing factor expression caused by hypoxia (i.e., SF1, SRSF1, SRSF3, and SRSF7) results in nearly 90% of IR-affected genes displaying high retention of introns in hypoxic compared with normal cells." (PMID 37506056, 2023). "Then, we analyzed the relationship between SRSF3 exon 4 splicing and hnRNP L exon 7 splicing in the head and neck cancer data of the TCGA database." (PMID 31828152, 2019). "Indeed, the ratio of SRSF3 exon 4 inclusion versus exclusion is positively and significantly correlated with the ratio of hnRNP L exon 7 inclusion versus exclusion in patients with head and neck cancer." (PMID 31828152, 2019).
liver fibrosis (4 papers, 2019 to 2024). "Serine-rich splicing factor 3 (SRSF3) modulates liver function, and the loss of SRSF3 deteriorates liver fibrosis and injury." (PMID 39697538, 2024). "The suppressed Srsf3 expression in MCD-fed iPla2β−/− mice was in line with observed exaggeration of liver fibrosis in these mice." (PMID 31409057, 2019).
melanoma (4 papers, 2021 to 2026). A malignant, usually aggressive tumor composed of atypical, neoplastic melanocytes. "Mechanistically, some SR proteins may be involved in regulating MDM4 splicing variants; however, SRSF3 is one of the most essential enhancers of exon 6 in melanoma cells." (PMID 38462618, 2024). "The splicing enhancer SRSF3 is necessary for the generation of MDM4-FL in melanoma cells." (PMID 34144037, 2021). "The splicing factor SRSF3 drives the inclusion of exon 6 in MDM4, whereas ASO-mediated skipping of exon 6 effectively reduces MDM4 levels and significantly inhibits melanoma growth." (PMID 41510173, 2026). "In melanoma, alternative splicing of MDM4 mRNA is regulated by serine/arginine-rich splicing factor 3 (SRSF3), which belongs to the SR protein family of splicing factors." (PMID 34144037, 2021).
pancreatic cancer (4 papers, 2020 to 2025). "The increased expression of SRSF3 enhances gemcitabine resistance of pancreatic cancer cells both in vitro and in vivo, whereas silence of SRSF3 by siRNAs exhibits an opposite effect." (PMID 37416784, 2023). "In pancreatic cancer, SRSF3 increases the expression of lncRNA ANRIL long isoform by recognizing its m6A modification." (PMID 37416784, 2023). "As expected, a rapidly increasing expression of the NMD-sensitive SRSF3 transcript was observed after CHX treatment in SF3B1-mutated cells originating from various cancer types (CLL, UM and pancreatic cancer)." (PMID 33585229, 2020). "SRSF3 is highly expressed in gemcitabine-resistant pancreatic cancer cells." (PMID 37416784, 2023). "Knockdown of SRSF3 leads to decrease m6A modification level of ANRIL in pancreatic cancer cells." (PMID 37416784, 2023).
steatosis (4 papers, 2020 to 2024). Increased lipid within the cytoplasm of cells. "SEs that were altered with steatosis or ballooning were significantly enriched for SRSF3-dependent SEs (OR 1.43, p = 0.0018; OR 1.31, p = 0.021; respectively) but were not enriched when analyzed by fibrosis or inflammation scores." (PMID 38291075, 2024). "In this study, STX17 was decreased in the liver of steatosis mice and STX17 protein was reduced by the loss of SRSF3." (PMID 36764525, 2023). "In view of the role of neddylation in regulating stabilization of SRSF3, MLN4924 can repress the degradation of SRSF3 and reduce the accumulation of SREBP1c, which alleviate the steatosis and prevent the progression of NAFLD." (PMID 33195347, 2020). "In this study we investigated the role of IGF2 in this liver phenotype and showed that loss of IGF2 reduced liver inflammation and fibrosis, but not steatosis, in mice lacking SRSF3 in hepatocytes." (PMID 35615981, 2022).